FLNB (filamin B)
Diseases named in the same sentence as FLNB in open-access papers (continued):
Sharing a sentence is not in itself a finding about the gene and the disease.
cancer (25 papers, 2011 to 2025). A tumor composed of atypical neoplastic, often pleomorphic cells that invade other tissues. "FLNA and FLNB were the most commonly mutated genes related to disulfidptosis in cancer, as revealed by the SNV analysis." (PMID 38584831, 2024). "This analysis revealed that IQGAP1, FLNB, and ACTB are involved in the “Proteoglycans in cancer” pathway, IQGAP1, ABI2, and ACTB are associated with the “Regulation of actin cytoskelet”, IQGAP1 and ACTB are linked to the “Adherens junction”." (PMID 40672380, 2025). "A previous study suggested that knockdown of FLNB in cancer cells decreased di-phosphorylation of MRLC and phosphorylation of FAK, then inhibited cell migration and focal adhesions." (PMID 38694875, 2024). "Multiple studies report a role for FLNA and FLNB in cancer cell migration, but the role of FLNC remains largely unexplored." (PMID 33934493, 2021). "Several studies have described that FLNA and FLNB interact with a number of proteins to regulate signaling events involved in cell shape and migration in cancer." (PMID 28031525, 2017). "Numerous studies have reported that expression of FLNA and FLNB promote cancer invasion and metastasis." (PMID 28031525, 2017). "The role of FLNB in cancer development is still a mysterious challenge." (PMID 38694875, 2024). "Moreover, editing events of these genes have been associated with cancer progression (e.g., AZIN1, COPA, CCNI, and FLNB) or neurological disorders (e.g., GRIK2 and GRIA2–4)." (PMID 35406793, 2022). "Finding out which FLNB protein is made in a given cancer may provide an indication of its aggressiveness." (PMID 30059005, 2018). "In addition, the strong association between FLNB splicing and EMT features suggest that FLNB exon 30 splicing may serve as a biomarker for residence of cancer cells in a mesenchymal state." (PMID 30059005, 2018). "Recent studies have suggested that RHOJ is preferentially expressed in epithelial-to-mesenchymal transition cells, with interaction with proteins (FLNB, TLN1 and IPO9) that regulate nuclear actin and inhibit actin polymerization in cancer cells." (PMID 39984455, 2025). "DSTN and FLNB were downregulated when ACTIN4, INF2, MHY10, FLNA, PDLIM1, and IQGAP1 were upregulated in THCA cancer tissues." (PMID 38584831, 2024). "The SNV landscape map revealed that the SNV of FLNA, FLNB, and MYH9 was frequently detected in various cancers." (PMID 38584831, 2024). "MHY9, INF2, FLNA, MYH10, FLNB, FLN1, and ACTB were upregulated in HNSC cancer tissues." (PMID 38584831, 2024). "Furthermore, by resorting to several recent review articles, there were 26 RESs with cancer‐related clinical significance that were covered by our dataset, which resided in 7 genes (AZIN1, BLCAP, COG3, COPA, FLNB, GRIA2, and NEIL1)." (PMID 34319007, 2021). "Finally, Filamin B (FLNB) was also identified in the gene expression and methylation analysis in both acute and chronic pooled transcriptome data and was significantly enriched in ‘cancer pathways’ in both the pooled transcriptome and methylome." (PMID 30862794, 2019). "When we examined all non-hematopoietic cancer cell lines in the CCLE, we found that the degree of FLNB exon 30 splicing correlated significantly with a ZEB1 target signature, an epithelial differentiation signature, two metastasis signatures and a mammary stem cell signature." (PMID 30059005, 2018).
skeletal dysplasia (9 papers, 2014 to 2025). Any Mendelian diseases that affects growth and development of the skeleton. "Mutations in FLNB cause a spectrum of skeletal dysplasia, from mild types, like SCT and LS, to severe types, such as AO1, AO3, and BD." (PMID 35832491, 2022). "Here, we present the crystallographically-resolved atomic structure of domains 16 and 17 of the human FLNb, and also how skeletal dysplasia associated mutations interfere in the structure and function of both FLNa and FLNb." (PMID 28652603, 2017). "Mutations in FLNB cause two types of skeletal dysplasias on the basis of their clinical presentation and genetic etiology." (PMID 24551245, 2014). "Autosomal dominant mutations of FLNB (missense mutations, small in-frame deletions or insertions) cause a group of skeletal dysplasias, including Larsen syndrome (LS; OMIM 150250), atelosteogenesis I and III (AOI and AOIII; OMIM 108720 and 108721), and boomerang dysplasia (BD; OMIM 112310)." (PMID 24551245, 2014). "The three members of this family (FLNA, FLNB and FLNC) are involved in both development and normal tissue homeostasis through regulating diverse processes including cell locomotion and integrin signaling, and mutations in the FLNB gene cause a broad range of skeletal dysplasias." (PMID 30059005, 2018).
infection (6 papers, 2012 to 2022). The state of being infected such as from the introduction of a foreign agent such as serum, vaccine, antigenic substance or organism. "Infection with lentivirus carrying either shRNA sequence led to downregulation of FlnB expression at both the mRNA and protein levels." (PMID 24551245, 2014). "Some of these interacting proteins play key roles in cytoskeleton organization (FLNB), vesicular traffic (DYNLT1, USO1), and SUMOylation (UBC9) suggesting an interaction of meningococci with these cellular functions during the intracellular phase of the infection cycle." (PMID 35765029, 2022).
bone disorder (2 papers, 2022). "Mutations in FLNB, however, were solely found in skeletal diseases, which strongly suggested its crucial role in the development of skeletal system." (PMID 35832491, 2022). "Our study demonstrated the pathogenic mechanisms of two novel FLNB variants in two different clinical settings and proved that FLNB variants could not only directly cause skeletal malformations but also worsen skeletal symptoms in the setting of other skeletal diseases." (PMID 35832491, 2022).
connective tissue disorder (2 papers, 2018 to 2023). A disease involving the connective tissue. "High throughput sequencing of 34 genes for hereditary connective tissue disorders did not identify any mutation in FLNB, but did identify a de novo missense mutation in TGFBR2 and a nonsense mutation in COL2A1 that was also present in his unaffected father." (PMID 30170566, 2018).
myopathies (2 papers, 2017 to 2019). "Also, while there are limited studies for the role of FLNB (filamin B) in skeletal muscle or resistance exercise induced hypertrophy, its loss has recently been highlighted to be associated with several myopathies and therefore a potential interesting target in skeletal muscle adaptation." (PMID 30862794, 2019). "Filamins are comprised of three homologous proteins—Filamin A, B, C. Human mutations in FLNB have been associated primarily with skeletal anomalies, whereas FLNC mutations cause myopathies." (PMID 29240780, 2017).
adenocarcinoma (1 paper, 2017). A common cancer characterized by the presence of malignant glandular cells. "As in silico findings demonstrated a causal relationship between FLNA and FLNB in PC-3 cells under conditions of hypoxia and lactic acid, the relationship between FLNA and FLNB levels was examined in patients with benign cases and in patients with adenocarcinoma." (PMID 28344825, 2017). "Last, in patients without PrCa, FLNA and FLNB blood levels were positively correlated, while in patients with adenocarcinoma the relationship is dysregulated." (PMID 28344825, 2017).
cardiovascular disease (1 paper, 2019). "We propose that the elevated expression of FLNB and the decline of editing in ADAR2-/- mouse heart tissues might be associated with the cardiovascular disease similar to FLNA." (PMID 31039163, 2019).
genetic disease (1 paper, 2023). "FLNB (Filamin B) is known for its role in atelosteogenesis type 1, a genetic disease characterized by a severe short-limbed dwarfism that is lethal in the perinatal period." (PMID 36800380, 2023).
immune diseases (1 paper, 2020). "We will further explore how BKCa channel knockdown affects the expression of ATP5A1 and filamin B in WJ-MSC-derived exosomes and verify the effect of this modification in other immune diseases." (PMID 33059770, 2020).
FLNB also shares sentences with these, for which no sentence is quoted: Renal cyst (8 papers); renal carcinoma (5); colon cancer (2); cyst (2); osteochondrodysplasia (2); schizophrenia (2); acute myeloid leukemia (1); acute myocardial infarction (1); alopecia (1); Alzheimer disease (1); atelosteogenesis type III (1); autism (1); autoimmune disease (1); autosomal dominant disease (1); basal cell carcinoma (1); Breast Invasive Carcinoma (1); cardiac hypertrophy (1); cardiomyopathy (1); colorectal adenocarcinoma (1); congenital diaphragmatic hernia (1); cortical blindness (1); craniosynostosis (1); cryptorchidism (1); developmental delay (1); diabetes (1); dilated cardiomyopathy (1); endolymphatic hydrops (1); esophageal cancer (1); familial partial lipodystrophy (1); germ cell cancer (1).
A further 27 diseases each share a sentence with FLNB in 1 paper.